INS (insulin)
Diseases named in the same sentence as INS in open-access papers (continued):
Sharing a sentence is not in itself a finding about the gene and the disease.
Insulin resistance (continued). "Thus, other non-insulin-based surrogate indicators of insulin resistance that are more widely available across health care settings include the calculation of the ratio of triglyceride to HDL-cholesterol (TG/HDL) and the triglyceride glucose index (TyG)." (PMID 36501139, 2022). "Therefore, further studies are warranted in order to verify the effectiveness of N. sativa on insulin secretion and/or insulin resistance." (PMID 36034891, 2022). "In summary, we found that some genes involved in glycolipid metabolism, insulin secretion, and insulin resistance had been epigenetically modified, which might contribute directly or indirectly to GDM." (PMID 35606885, 2022). "Vitamin D might be only beneficial in individuals with normal glucose tolerance because the development of T2D consisted of progressive insulin resistance, which was initially compensated by enhanced insulin secretion." (PMID 36643972, 2022). "T2D is characterized by high levels of plasma glucose caused mainly by pancreatic β-cell dysfunction and inefficient action of insulin, known as insulin resistance (IR), which occurs in cells of insulin-sensitive key organs and tissues such as the heart or skeletal muscle." (PMID 35955920, 2022). "The insulin resistance that developed in concordance with developing hypoglycemia may represent a defense mechanism, preventing any further lowering of the blood sugar by insulin." (PMID 36548717, 2022). "Similarly, HBOT was able to improve insulin sensitivity and reverse insulin resistance along with many other MDs parameters rats with abdominal obesity, induced by sucrose induced metabolic syndrome in rats." (PMID 36590387, 2022). "This condition is also due to insulin resistance; in fact, a significantly lower insulin sensitivity index after oral tolerance testing and increased pancreatic insulin synthesis have been demonstrated in several studies to compensate the lack of glucose clearance." (PMID 35628968, 2022). "The insulin levels and insulin resistance scores were the highest in patients with UM." (PMID 36003786, 2022). "It is postulated that in insulin resistance such as type 2 diabetes, excess insulin may in part be responsible for enhanced ACC activity." (PMID 36295842, 2022). "However, the plasma insulin, blood glycated hemoglobin (HbA1c), and homeostasis model assessment of insulin resistance (HOMA-IR) levels were markedly lower in the HFD+SREA group by 51.2%, 17.3%, and 67.3%, respectively, compared to that in the HFD group." (PMID 35454963, 2022). "RA thereby suppresses insulin resistance and weight gain, in opposition to insulin effects." (PMID 35458115, 2022). "This could be explained as leading to spike in insulin which worsen insulin sensitivity overtime thereby enhancing insulin resistance leading to hyperglycaemia." (PMID 36992739, 2022). "Moreover, various studies have indicated that O-GlcNAcylation of different signaling intermediates, such as IRS1 and Akt, negatively regulate insulin signaling and contribute to insulin resistance." (PMID 36058931, 2022). "One good quality study reported that Se supplementation resulted in a significant reduction in serum insulin levels, fasting plasma glucose, and homeostasis model of assessment- (HOMA-) insulin resistance and a significant increase in quantitative insulin sensitivity check index." (PMID 35571749, 2022). "We found glycine levels to be significantly lower in older adults compared to that of young subjects and to be inversely correlated with insulin resistance; glycine levels were 15.5% lower in plasma, an extent that is similar to what has been described in obese, insulin-resistant subjects." (PMID 35821844, 2022). "However, high-sugar diets tended to exacerbate the insulin response to glucose, suggesting the development of insulin resistance." (PMID 35942169, 2022).
Insulin resistance (continued). "These factors are known to affect insulin sensitivity, which indicates that insulin resistance may play a key role in the pathogenesis of LADA." (PMID 35837301, 2022). "However, in the in vivo models of insulin resistance, insulin signaling leads to expansion of bone marrow adipose tissue, decreased trabecular bone mineral density (BMD), and decreased cortical thickness." (PMID 36278482, 2022). "In those tissues an uncontrolled reduction of intracellular ROS by a higher-than-physiological GPx1 expression might desensitize insulin signalling; this desensitization leads to insulin resistance in the context of T2D." (PMID 35204134, 2022). "Additionally, we found that the strains elevated in PCOS also expressed the SREBP1 protein, by which, directly perturbing insulin signaling pathway and inducing insulin resistance." (PMID 36338055, 2022). "The remission of hyperglycemia and peripheral insulin resistance, on the one hand, results in a decreased insulin demand, which could relieve β-cells from overloaded insulin production and reduce ER stress." (PMID 35929791, 2022). "Furthermore, since insulin is crucial for regulation and metabolism, organs like the liver are particularly impacted in people with systemic insulin resistance." (PMID 36387912, 2022). "In addition, insulin resistance needs fasting plasma insulin (FPI) level determination by Chemiluminescence immune Assay (CLIA) which is not available in our set up." (PMID 37092108, 2022). "For PCOS with insulin resistance, metformin can be used to improve insulin sensitivity by increasing the activity of insulin receptor tyrosine kinase, which further activates post-receptor insulin signaling pathways at a molecular level." (PMID 35564864, 2022). "To clarify the effect of insulin resistance on the expression level of PPARδ, we used RT-PCR and Western blot to detect the expression level of PPARδ in the liver tissues of db/db mice and in an insulin-resistant HepG2 cell model." (PMID 36051387, 2022). "The inverse associations with insulin sensitivity were of special interest for Hispanic youth because insulin resistance can occur in Mexican children without evidence of overweight or obesity." (PMID 35215546, 2022). "Another interesting finding here was that steadily low salt intake might increase fasting insulin and subsequently increase insulin resistance (p<0.01)." (PMID 35784580, 2022). "An exercise intervention program proved to be effective in the treatment of insulin resistance in individuals with overweight/obesity, metabolic syndrome or type 2 diabetes, i.e., reduces fasting insulin, HOMA-IR, fasting blood sugar, HbA1c, and body mass index." (PMID 35677551, 2022). "Likewise, an increase in fasting insulin and insulin resistance was observed with increasing age and BMI in children with PWS." (PMID 35150573, 2022). "However, it is possible that specific plasma ceramide species impact insulin sensitivity via incorporation into muscle ceramide species, where specific species are thought to be more potent in inducing insulin resistance." (PMID 36030929, 2022). "Insulin signaling is impaired by metainflammation due to the increase in body fat mass; however, adipose tissue seems to wield under insulin resistance with a pleiotropic effect by the production of bioactive molecules that behave like hormones, known as adipokines." (PMID 35326098, 2022). "Be that as it may, the effects of CaVγ4 on plasma insulin levels and insulin responsive peripheral tissues are unclear, since insulin resistance is highly related to prediabetes which is marked by IFG and IGT." (PMID 35453520, 2022). "Previous studies have shown that Black Americans are less sensitive to insulin and have a higher risk of insulin resistance compared to non-Hispanic whites." (PMID 35836938, 2022).
Insulin resistance (continued). "However, chronic inflammation is known to induce pancreatic β-cell injury and dysfunction, inhibit insulin-mediated glucose uptake and lead to hepatic insulin resistance, as characterized by impaired insulin-induced suppression of hepatic gluconeogenesis." (PMID 36145139, 2022). "Because muscle insulin resistance differs considerably among humans with obesity, differences in insulin resistance among subjects with obesity may explain discrepant finding in muscle protein synthesis in obesity reported across studies to date." (PMID 35350688, 2022). "Thus, it is assumed that not only insulin signaling but also IGF-1 signaling are impaired in patients with insulin resistance." (PMID 36198696, 2022). "Since insulin is a well-known growth factor, probably hyperinsulinemia and insulin resistance may contribute to IVS thickening." (PMID 36568107, 2022). "The enhanced adipose tissue lipolysis characteristic of obesity could result from insulin resistance but also may contribute to insulin resistance due to the detrimental effect of excess fatty acids on insulin signaling." (PMID 35625574, 2022). "Likewise, patients with peripheral insulin resistance due to obesity or T2D showed a reduced response to intranasal insulin in the CNS, as measured by functional neuroimaging methods." (PMID 35741464, 2022). "It should be noted that, FFA is a well-known marker of insulin resistance, it could blunt the hypoglycemic effect of insulin by increasing beta-oxidation in the mitochondrial." (PMID 35574029, 2022). "Indeed, over 10 years ago, it was recognized that AVP levels significantly correlated with several markers of the metabolic syndrome, i.e., body mass index, fasting plasma glucose and insulin concentrations, insulin resistance, and triglyceride levels." (PMID 35656391, 2022). "Insulin resistance in mammals is classically defined as an inadequate response of the insulin-sensitive tissues, that is, those tissues (skeletal muscle, liver, and fat) whose glucose handling is regulated by insulin, resulting in the maintenance of euglycemia." (PMID 35884888, 2022). "In support of such a hypothesis, insulin increased the formation of IL-1β in U937 macrophages and thereby impaired the insulin-dependent induction of glucokinase in a cell-based model of hepatic insulin resistance." (PMID 35955975, 2022). "Therefore, it has been suggested that a possible connection between metabolic and cognitive dysfunctions is caused by reductions in the sensitivity of central neuronal pathways to insulin, also known as brain insulin resistance." (PMID 36505102, 2022). "Under a hyperglycemic environment, ROS activates the NLRP3 inflammasome in β cells, elevating caspase-1-dependent IL-1β secretion; this mediates dysfunction of β-cell insulin secretion and promotes obesity and insulin resistance, finally leading to pyroptosis and the development of T2DM." (PMID 35355717, 2022). "Activation of Sirt3 by its activator, HNK, improves insulin sensitivity via enhancing lipolysis and glucose transport, which might be beneficial for treatment of insulin resistance or type 2 diabetes." (PMID 35409099, 2022). "The Beijing Child and Adolescent Metabolic Syndrome Study (BCAMS) showed that poor sleep is associated with higher body mass index (BMI), fasting glucose, insulin, and Homeostatic Model Assessment for Insulin Resistance (HOMA-IR) among 3166 school children aged 6–12." (PMID 35163627, 2022). "Furthermore, serum ANGPTL8 was higher in individuals with insulin resistance than in those with insulin sensitivity." (PMID 35851270, 2022). "Of note, patients with psoriasis with normal blood glucose levels demonstrate insulin resistance or impaired insulin sensitivity, which may potentially result in the development of diabetes mellitus." (PMID 36012327, 2022).
Insulin resistance (continued). "Although there is evidence to support the role of insulin resistance in the promotion and progression of cancer, we did not observe any associations between insulin, glucose, and the HOMA‐IR index with disease‐free survival or overall survival." (PMID 35174651, 2022). "Insulin resistance could then stress the beta-cells, as greater insulin secretion would be necessary to maintain glucose tolerance." (PMID 35163746, 2022). "The effect of vitamin D on insulin resistance may be explained by its effect as a potential regulator of insulin secretion and Ca2+ levels." (PMID 35546181, 2022). "A decrease in insulin resistance through insulin-sensitizing drugs (such as metformin, rosiglitazone, pioglitazone, and D-chiro-inositol) could improve the reproductive and metabolic outcomes of patients with PCOS." (PMID 36523600, 2022). "However, we find that MEF‐secreted leptin is insufficient to fully rescue insulin resistance in FF mice, measured by the AUC of the fasting insulin tolerance test." (PMID 35844058, 2022). "Since varied manifestations of GDM may stem from different pathophysiological mechanisms (insulin resistance versus impaired insulin secretion), adipokine production may also differ for various GDM phenotypes." (PMID 35566542, 2022). "Therefore, insulin plays a key role in the control of hepatic lipid metabolism and the development of hepatic steatosis during insulin resistance." (PMID 36273126, 2022). "To investigate whether IR puncta are altered in insulin resistance, we compared the insulin-sensitive HepG2 cells to cells in which an insulin-resistant state was induced by hyperinsulinemia." (PMID 36473871, 2022). "Thus, it has been shown that in adipose tissue insulin resistance determined by the impairment of insulin-dependent suppression of lipolysis correlated with the size of adipocytes but not with the macrophage number in adipose tissue." (PMID 35955975, 2022). "Insulin resistance developed in the liver and visceral white adipose tissue, but cardiac insulin signaling continued to be enhanced, and excessive insulin signaling mediated detrimental effects through induction of pathological cardiac hypertrophy and ischemia in heart." (PMID 35012677, 2022). "Previous reports demonstrated that elevated circulating A-FABP values positively correlated with the low HDL-C level and high BMI, waist circumference, BP, total cholesterol, TG, LDL-C, insulin levels, and homeostasis model assessment-estimated insulin resistance (HOMA-IR) values." (PMID 35954815, 2022). "However, studies of short- (3 days) and intermediate-term (3–5 weeks) KD found impaired insulin tolerance and hepatic insulin resistance in mice and rats." (PMID 35433789, 2022). "CRP could destroy the intracellular insulin signal and lead to the accumulation of insulin resistance, hyperglycemia and advanced glycation end products." (PMID 36131931, 2022). "Furthermore, the mice fed an HFD also exhibited impaired insulin signaling and insulin resistance, since insulin signaling is impaired by the accumulation of lipids in the liver." (PMID 35745260, 2022). "Furthermore, these two phytochemicals attenuated insulin resistance via increasing the insulin sensitivity, Akt, and glycan synthse kinase-3 (GSK3) β and decreasing insulin receptor substrate 1 (IRS-1) phosphorylation." (PMID 36028892, 2022). "In addition to the defects in central insulin signalling, it has also been suggested that systemic insulin resistance and hyperinsulinemia also impacts brain energy metabolism and memory." (PMID 35805109, 2022). "Apo C-III expression is inhibited by insulin and, therefore, obese patients’ insulin resistance could explain the Apo C-III increase." (PMID 36145147, 2022). "This may be due to pathway-selective insulin resistance with inhibition of nitric oxide synthase stimulation but persistent insulin stimulation of endothelin release." (PMID 34957859, 2022).
Insulin resistance (continued). "However, as physiological insulin resistance increases during pregnancy, the insulin response becomes inadequate." (PMID 34983464, 2022). "The untreated group was unable to lower their blood glucose level showing the characteristic of insulin resistance, while the metformin and both doses of aqueous extract (500 mg/kg and 800 mg/kg) improved the insulin sensitivity in the body of all treated groups." (PMID 36079819, 2022). "In addition, glucose toxicity is involved in the development of insulin resistance by suppressing insulin signaling in insulin target organs." (PMID 35918386, 2022). "In insulin resistance, insulin loses the ability to promote the degradation of apoB." (PMID 36359273, 2022). "Metformin, a drug widely used to treat insulin resistance, and training that combines aerobic and strength exercise modalities (i.e., concurrent training) may improve insulin sensitivity." (PMID 36361210, 2022). "These mice displayed reduced insulin secretion, insulin resistance, and glucose intolerance." (PMID 35055468, 2022). "When insulin resistance occurs, insulin or IGF-1 signaling is inhibited." (PMID 35846289, 2022). "DM results in increased blood sugar levels attributed to the non-functioning of the insulin-producing islet cells of the pancreas (type 1 DM) and insulin resistance, among other causes." (PMID 35747025, 2022). "To understand whether changes in hepatic insulin resistance were accompanied by changes in systemic insulin sensitivity, we evaluated fasting glycemia and insulinemia, and the HOMA index." (PMID 35883786, 2022). "High ALT values are related to hepatic insulin resistance and could prospectively predict decreased hepatic insulin sensitivity and the development of type 2 diabetes." (PMID 36408044, 2022). "The main pathological manifestations of 1α(OH)ase-null mice were glucose overproduction and insulin resistance in the liver in the present study, although the serum insulin did not appear abnormal in the 1,25(OH)2D3-deficient mice." (PMID 35132380, 2022). "An experimental study showed that dietary calcium intake could increase the extracellular calcium, which affects the beta cells of pancreas and improve insulin secretion and insulin resistance." (PMID 35268061, 2022). "Thus, they suggested that perhaps increased insulin secretion brought forth by increased GLP-1 availability is responsible for the onset of insulin resistance in some horse." (PMID 35906619, 2022). "Insulin resistance (IR) is defined as an impaired response of target cells to insulin." (PMID 36368970, 2022). "Meanwhile, insulin resistance is one of the variables in the metabolic syndrome associated with NAFLD and it is defined as a decrease or insufficient insulin sensitivity in the target tissues, such as muscle, adipose tissue, and liver, towards glucose uptake from the blood." (PMID 35779187, 2022). "In addition, BRD2 suppresses Deptor expression, thereby activating the mTORC1 pathway, leading to feedback inhibition of insulin signaling and promoting insulin resistance." (PMID 36015180, 2022). "Elevated plasma free fatty acids (FFAs) is considered an important etiologic factor linking insulin resistance, oxidative stress, and inflammation with obesity and other cardiometabolic disorders, and impaired insulin-mediated glucose uptake correlates with circulating FFA levels." (PMID 35055038, 2022). "Thus, insulin abnormalities and insulin resistance are key drivers of the development of HF in T2D, and thereby represent possible therapeutic targets." (PMID 35941584, 2022). "These substances may represent a complementary approach, along with life-style intervention such as exercise and nutrition, aimed at enhancing glucose control, lowering insulin resistance and improving insulin sensitivity." (PMID 35600880, 2022). "Insulin and insulin resistance will be discussed directly in section." (PMID 36457554, 2022).